BMAL1 (basic helix-loop-helix ARNT like 1)
Diseases named in the same sentence as BMAL1 in open-access papers (continued):
Sharing a sentence is not in itself a finding about the gene and the disease.
Listeria monocytogenes infection (1 paper, 2024). "Moreover, in a model of Listeria monocytogenes infection, Bmal1 was shown to regulate the circadian rhythm of monocyte recruitment to tissues." (PMID 39519024, 2024).
liver inflammation (1 paper, 2023). "It is evidenced that the overexpression of the core component of the Circadian rhythm Bmal1 obviously attenuates mycotoxin-induced liver inflammation and liver injury." (PMID 38203339, 2023).
long QT syndrome (1 paper, 2021). "This study determined how inducing the deletion of Bmal1 in adult cardiomyocytes impacted the in vivo electrophysiological phenotype of a knock-in mouse model for the arrhythmogenic long QT syndrome (Scn5a+/ΔKPQ)." (PMID 34248669, 2021). "In this study, we determined how inducing the deletion of Bmal1 in adult cardiomyocytes impacted cardiac electrophysiology in a genetic mouse model of long QT syndrome (LQTS)." (PMID 34248669, 2021).
lung diseases (1 paper, 2025). "Disruption of circadian rhythms has been linked to various lung diseases, and the circadian clock gene Clock-Bmal1 has been shown to regulate cellular responses to inflammation and immune activation in the lungs." (PMID 40110037, 2025).
lupus (1 paper, 2024). "We assessed if lupus clinical parameters correlate with BMAL1 expression in peripheral blood neutrophils obtained from SLE patients." (PMID 39664388, 2024). "Given the evidence implicating neutrophils in the pathogenesis of lupus, we hypothesized that disruptions in neutrophils’ circadian rhythm through Bmal1 disruption may be pathogenic in SLE." (PMID 39664388, 2024). "Taken together, these observations suggest that Bmal1 regulates neutrophil maturation in the bone marrow in murine models of lupus." (PMID 39664388, 2024). "Overall, the data in lupus patients is consistent with findings in murine lupus suggesting that BMAL1 may negatively regulate autoantibody production." (PMID 39664388, 2024). "We assessed the role of Bmal1 in clinical and immunologic manifestations of murine lupus and in human SLE neutrophils." (PMID 39664388, 2024). "Myeloid-conditional Bmal1 knockout mice (Bmal1Mye−/−) and wild type (WT) were treated with epicutaneous TLR7/8 agonist (imiquimod; IMQ) for 6 weeks to induce a lupus phenotype." (PMID 39664388, 2024). "We report that Bmal1, a clock gene, negatively regulates autoantibody production in a TLR-7/8-dependent model of lupus." (PMID 39664388, 2024). "We used an induced model of murine lupus triggered by epicutaneous administration of the TLR7/8 agonist imiquimod (IMQ) and investigated lupus phenotype in wild type (WT) and Bmal1-myeloid conditional KO mice (Bmal1Mye−/−)." (PMID 39664388, 2024). "In summary, although the absence of Bmal1 in myeloid cells did not dramatically modify murine lupus symptoms during the 6 weeks of treatment, it led to increase anti-dsDNA antibody levels, renal immune complex deposition, and enhanced dermal tissue neutrophil infiltration." (PMID 39664388, 2024).
lupus nephritis (1 paper, 2025). Glomerulonephritis in the context of systemic lupus erythematosus. "By suppressing ROR-driven BMAL1 transcription, it reduces IL-17 production in autoimmune models–a mechanism particularly relevant for uveitis and lupus nephritis." (PMID 40496242, 2025).
lymphoblastic leukemia (1 paper, 2017). "A survey of cells with hypermethylated CpG islands in the BMAL1 promoter found that the human lymphoblastic leukemia cell line, RPMI8402, has methylated CpG islands." (PMID 28487473, 2017).
mesothelioma (1 paper, 2009). A usually malignant and aggressive neoplasm of the mesothelium which is often associated with exposure to asbestos. "We also found concomitant BMAL1 and TYMS overexpression indicating that this clock gene may also be an important driver of mesothelioma progression." (PMID 19662092, 2009).
mitochondrial dysfunction (1 paper, 2024). "Noteworthily, the downregulation expression of Bmal1 was accompanied by corneal endothelial dysfunction and mitochondrial dysfunction under SD conditions." (PMID 38907352, 2024).
Multiple Organ Failure (1 paper, 2020). A progressive condition usually characterized by combined failure of several organs such as the lungs, liver, kidney, along with some clotting mechanisms, usually postinjury or postoperative. "Although circadian rhythm disruption-driven coagulation prevents the extravasation of S. oralis, more macrothrombusus is induced than in the control group, which leads to multiple organ failure on account of deduced BMAL1 expression." (PMID 33042871, 2020).
nephrolithiasis (1 paper, 2016). The presence of a calculus in the pelvis of the kidney; this is most often composed of mineral salts and proteins. "This percentage may increase by screening nephrolithiasis patients for mutations in USP2 or in clock genes controlling its expression such as ARNTL (BMAL1) and CLOCK and their binding sites in the promoter of USP2." (PMID 26756164, 2016).
Obstructive sleep apnea (1 paper, 2025). "Obstructive sleep apnea (OSA), characterized by intermittent hypoxia and arousal-related sympathetic surges, further destabilizes autonomic and vascular rhythms and shifts the expression of core clock genes (BMAL1, CLOCK, PER1, CRY1), reinforcing blunted or inverted BP profiles." (PMID 41354885, 2025).
oral cancer (1 paper, 2025). "For example, the expression of core genes responsible for regulating the circadian clock (such as Clock, Bmal1, Per, and Cry) tends to decline in oral cancer, while some tumor-related genes (such as Reverb) are upregulated, indicating that circadian rhythm is dysregulated." (PMID 40282437, 2025).
oral squamous cell carcinoma (1 paper, 2024). "Per1, a negative regulator of Bmal-1, has been demonstrated to promote ferroptosis in the experiments of oral squamous cell carcinoma, which shows that Bmal-1 functions as a ferroptosis prohibitor." (PMID 39296207, 2024).
ovarian disorder (1 paper, 2022). A disease involving the ovary. "If this is the case, the positive feedback regulation between LHCGR and BMAL1 will expand the ovarian disorder induced by hypoxia." (PMID 36620217, 2022).
ovarian dysfunction (1 paper, 2022). The inability of the ovaries to function. "CLOCK, BMAL1, and E4BP4 can be entrained by hypoxic signaling, which synergistically promotes LHCGR reduction in GCs and results in ovarian dysfunction." (PMID 36620217, 2022).
paroxysmal AF (1 paper, 2021). "The expression of BMAL1, CRY2, NR1D2, PER2, and RORA was significantly lower in patients with persistent AF than in those with paroxysmal AF (persistent AF vs. paroxysmal AF, all p < 0.05)." (PMID 33430447, 2021). "In detail, the expression of BMAL1, RORC, and TIM genes was significantly lower in patients with persistent AF than in those with paroxysmal AF or no AF (persistent AF vs. paroxysmal AF and persistent AF vs. no AF, all p < 0.05)." (PMID 33430447, 2021).
postpartum depression (1 paper, 2025). A type of clinical depression that occurs after childbirth. "The BMAL1 c.141-2A>G variant in Individual #1 was inherited from a mother who had an unremarkable medical history other than postpartum depression." (PMID 40720646, 2025).
Prader-Willi syndrome (1 paper, 2024). "Although G6PDS188F variant did not prevent the loss of HFD-induced Bmal1 expression, intriguingly it increased Magel2, a circadian clock-controlled gene whose disruption results in some of the characteristics of Prader-Willi Syndrome." (PMID 38876306, 2024).
radiation-induced gastrointestinal syndrome (1 paper, 2024). "BMAL1 knockout mice also exhibit reduced small intestinal crypts and impaired intestinal regeneration after radiation-induced gastrointestinal syndrome, highlighting the importance of BMAL1 in intestinal cell proliferation." (PMID 38678017, 2024).
respiratory infection (1 paper, 2015). "To dissect the role of clock regulatory proteins in response to respiratory infection, we measured the response of BMAL1 KO mice and wild-type littermates to IAV infection." (PMID 25923474, 2015).
retinal degeneration (1 paper, 2025). Degeneration of the retina. "Bmal1, a key transcriptional regulator of the circadian clock, serves as a critical pathologic cofactor in retinal degeneration." (PMID 41243864, 2025). "This not only elucidates a connection between circadian clock dysfunction and retinal degeneration but also potentially promises an avenue for the restoration of vision in retinal degeneration through the targeted manipulation of the clock gene Bmal1." (PMID 41243864, 2025). "This review presents recent findings and evidence regarding the contributory role of Bmal1 in retinal degeneration and its deficits, while exploring its therapeutic potential." (PMID 41243864, 2025).
retinal diseases (1 paper, 2025). "Bmal1 is a core clock gene that plays a critical role in regulating circadian rhythms, and its dysregulation has been linked to various pathophysiological processes of retinal diseases." (PMID 41243864, 2025). "Deficiency in Bmal1 contributes to a broad spectrum of retinal pathological alterations, and modulating the clock gene Bmal1 could potentially inform innovative treatment strategies for retinal diseases." (PMID 41243864, 2025). "Future research is required to identify effective Bmal1 regulators and to develop effective interventions for a range of retinal diseases." (PMID 41243864, 2025). "The mounting body of evidence indicates that Bmal1 serves as a bridging factor between circadian rhythms and retinal diseases, providing novel insights into the development of circadian‐based therapeutic strategies." (PMID 41243864, 2025). "Bmal1 has emerged as a promising target for the treatment and prevention of retinal diseases." (PMID 41243864, 2025). "These key factors, which are regulated by Bmal1, play a crucial role in retinal diseases." (PMID 41243864, 2025). "Ongoing investigations across diverse animal models indicate that Bmal1 is implicated in the pathogenesis of retinopathy, highlighting that targeting Bmal1 gene‐related loci or Bmal1 expression itself could be pertinent to treating retinal diseases." (PMID 41243864, 2025). "In this context, targeting the Bmal1 gene could act as a viable approach to address retinal diseases." (PMID 41243864, 2025). "Importantly, accumulating evidence suggests that Bmal1 plays a crucial role in various pathological processes of retinal diseases, including the regulation of mitochondrial homeostasis and energy metabolism." (PMID 41243864, 2025).
skin cutaneous melanoma (1 paper, 2023). "Similar associations were found for the overall survival (OS), where significantly higher expression levels of NR1D2 and BMAL1 were associated with longer survival among skin cutaneous melanoma patients." (PMID 37373286, 2023). "BMAL1 is physiologically downregulated during activation of NF-κB-related inflammatory responses through p65 subunit phosphorylation, but our analysis showed a positive correlation between the expression of NF-κB and BMAL1 in both primary and metastasis cutaneous melanoma." (PMID 37373286, 2023).
squamous cell tumours (1 paper, 2019). "BMAL1 loss also causes stem cell arrhythmia in squamous cell tumours." (PMID 31014368, 2019).
streptococcal pneumonia (1 paper, 2022). A febrile disease caused by streptococcus pneumoniae. "The Ray group has shown that knocking out the clock component Bmal1 in mouse myeloid cells is protective against streptococcal pneumonia." (PMID 35169890, 2022).
teratoma (1 paper, 2020). A non-seminomatous germ cell tumor characterized by the presence of various tissues which correspond to the different germinal layers (endoderm, mesoderm, and ectoderm). "Haematoxylin and eosin–stained sections of teratomas showed that a range of cell types and tissues from all three germ layers (i.e., mesoderm, ectoderm, and endoderm) was present in all teratomas regardless of BMAL1 presence." (PMID 32284354, 2020).
thyroid (1 paper, 2021). "The expression levels of CLOCK, BMAL1 and PER2 in thyroid malignant group were significantly higher than benign and normal groups, while CRY2 was decreased, p < 0.05." (PMID 34211057, 2021). "We then chose CLOCK, BMAL1, CRY1, CRY2, PER1 and PER2 to observe the changes of circadian rhythm genes in thyroid malignant tissues." (PMID 34211057, 2021).
thyroid tumor (1 paper, 2015). A benign or malignant neoplasm affecting the thyroid gland. "All these pathways are disrupted in various malignancies and are implicated in cancer development; the observed changes in BMAL1 expression in thyroid tumors may result in disturbances in these pathways." (PMID 25868389, 2015). "These correlations further underscore a potential link between BMAL1 expression and possibly function, as well as thyroid tumor progression, and strongly argue that the observed correlations might have functional significance." (PMID 25868389, 2015).
trauma (1 paper, 2024). "Consistent with other studies, miR-155 was reported to bind to the 3’UTR of Bmal1 in macrophages to orchestrate the circadian clock and promote the inflammatory response; inhibition of miR-155 upregulated Bmal1 and alleviated brain trauma induced by cerebral hemorrhage." (PMID 38150082, 2024).
tubular adenoma (1 paper, 2022). A usually polypoid neoplasm arising from the glandular epithelium. "Notably, Apc+/−;Bmal1−/− mice showed a marked increase in neoplastic changes, ranging from ACFs and tubular adenomas to locally invasive adenocarcinomas extending into the muscularis propria." (PMID 35947664, 2022).
Ureteral obstruction (1 paper, 2025). Obstruction of the flow of urine through the ureter. "They suggested that this reduction could be linked to alterations in the rhythmic expression of Bmal1 after unilateral ureteral obstruction, and that BMAL1 protects against obstructive renal fibrosis by suppressing Gli2 transcription." (PMID 39858471, 2025).
vitamin A deficiency (1 paper, 2022). Deficiency of vitamin A due to malnutrition, malabsorption, or dietary lack. "Vitamin A deficiency reduced the level of RXRβ mRNA, changed the rhythm amplitude of the PER1, REV-ERB genes and REV-ERB protein, and phase-shifted the daily peaks of RORα protein as well as BMAL1, RORα, RC3 and BDNF mRNA levels." (PMID 36466383, 2022).
tumor (207 papers, 2009 to 2026). "The study uses a combination of genetic models, organoid assays, and transcriptomic profiling to demonstrate that the loss of Bmal1 disrupts circadian rhythms and increases tumor initiation." (PMID 40589644, 2025). "For instance, studies have shown that mutations in CLOCK and BMAL1 can either enhance or suppress tumor growth, depending on the specific context and tissue type." (PMID 41174721, 2025). "Melatonin demonstrates upregulation of mRNA levels of Clock, and Per2, and downregulation of Bmal1 mRNA, thereby suggesting a protective effect on rhythm loss during tumor progression." (PMID 39012661, 2024). "Observed properties from BMAL1 was linked to its ability in autophagy induction as high magnitudes of autophagosomes detected in tumour cells." (PMID 38336976, 2024). "The results of in vivo detection markers, including PTGS2 mRNA levels and MDA quantification, suggested that knocking down BMAL1 increased tumor cell susceptibility to ferroptosis." (PMID 38703241, 2024). "Loss of Bmal1 in a mouse model of human CRC accelerated tumor development and increased intestinal proliferation, possibly via increased Yap activity." (PMID 39272783, 2024). "Recent studies have established the association of BMAL1 with tumor initiation, progression, and metastasis, as well as its correlation with chemotherapy resistance in tumor cells." (PMID 38703241, 2024). "The finding showed that theloss of BMAL1 and Per2 further increased tumor burden and decreasedsurvival, which comparatively had a greater impact in the BMAL1-mutated group." (PMID 39072055, 2024). "Although F4/80+ tumor‐associated macrophages (TAMs) were slightly decreased in tumors grown in Bmal1−/− mice." (PMID 37330661, 2023). "Concurrently, melatonin, a drug used to treat various diseases and inhibit tumor growth, prevents BMAL1 expression, an effect potentially associated with the upregulation of MT receptors and the decrease in Hif-1α138." (PMID 36647780, 2023). "Conversely, some studies have shown that Bmal1 deficiency or circadian photoperiod disruption increased tumor initiation." (PMID 36982509, 2023). "Concordant with the aggressive tumor phenotype, Bmal1 mutation also caused resistance to chemotherapy." (PMID 37262074, 2023). "In a novel mouse model, where exons 1 to 15 inApc were deleted in one allele (Apcex1-15/+),Bmal1 knockout increased tumor incidence, enlarged polyps and decreased survival (Chun, Fortin, Fellowset al., 2022)." (PMID 39282509, 2023). "Disruption of the circadian clock function is linked to tumorigenesis in several studies with CLOCK and BMAL1 harboring tumor-suppressive roles." (PMID 35126099, 2021). "Although the efficacy of an anti-HSP90 drug is lost in a Bmal1-deficient tumor, we cannot exclude the possibility that host factors also affect temporal efficacy." (PMID 33579708, 2021). "In fact, two recent and complementary studies showed that either chronic jet lag or genetic ablation of BMAL1 in myeloid cells led to an increase in pro-tumorigenic tumor-associated macrophages and faster tumor growth." (PMID 34299381, 2021). "The loss of the intact circadian clock during tumor progression probably diminished the influence of BMAL1-KD on SW620 cells compared to SW480 cells." (PMID 34065633, 2021). "BMAL1, which is one of the most important circadian clock genes, regulates overall circadian oscillations in humans, and previous reports have suggested that reduced BMAL1 is closely associated with tumor progression in cancer cells." (PMID 32316196, 2020). "All these findings revealed a causal relationship between Bmal1 and the efficiency of anti-tumor drugs." (PMID 32522976, 2020).